RNU6-502P (RNA, U6 small nuclear 502, pseudogene)
Gene: Small nuclear RNA gene on chromosome 6 (26,519,351 to 26,519,458, reverse strand). Ensembl gene ENSG00000199289.
Homologues: Orthologues: chimpanzee U6 (98% identical), macaque U6 (94% identical), rabbit U6 (86% identical). Paralogues in human: RNU6-11P (84% identical), RNU6-15P (84% identical), RNU6-37P (84% identical), RNU6-7 (84% identical), RNU6-8 (84% identical), RNU6-812P (84% identical), RNU6-87P (84% identical), RNU6-1 (83% identical), RNU6-2 (83% identical), RNU6-25P (83% identical), RNU6-38P (83% identical), RNU6-39P (83% identical), and 1287 more.